SIRT1 (sirtuin 1)
Diseases named in the same sentence as SIRT1 in open-access papers (continued):
Sharing a sentence is not in itself a finding about the gene and the disease.
rectal cancer (3 papers, 2018 to 2025). A primary or metastatic malignant neoplasm that affects the rectum. "In contrast, in colon and rectal cancer tissues, low expression of SIRT1 was closely associated with tumor differentiation, TNM stage, and distant metastasis (p < 0.05)." (PMID 41020376, 2025). "Association between SIRT1 expression and clinicopathological data of patients with rectal cancer." (PMID 41020376, 2025). "Rectal cancer patients showed a positive correlation between SIRT1 and CD4+ T cells (r = 0.319), CD8+ T cells (r = 0.109), macrophages (r = 0.509), and neutrophils (r = 0.282)." (PMID 41020376, 2025). "Plasma SIRT1 expression was 3.33 ± 1.35 ng/mL in 66 patients with rectal cancer, including 36 males and 30 females, aged 22–83 (59.50 ± 15.40) years." (PMID 41020376, 2025). "SIRT1 plasma concentration in rectal cancer patients was found to be lower in the low differentiation group [(2.84 ± 1.35) ng/mL vs. (3.69 ± 1.25) ng/mL, p = 0.011] than in the moderate and high differentiation groups." (PMID 41020376, 2025). "Correlation between serum SIRT1 and tumor markers in patients with rectal cancer." (PMID 41020376, 2025). "SIRT1 rs12778366 was not statistically associated with the risk of proximal colon and rectal cancer in women, though hazard ratios were also below one." (PMID 30410074, 2018). "Similarly, significant correlations were found between SIRT1 levels and CEA, CA199 in both colon and rectal cancer patients (p < 0.05)." (PMID 41020376, 2025). "We focused on clinicopathological factors and PTEN, SIRT1, p-4E-BP1, and pS6 protein expression assessed by immunohistochemistry in 73 rectal cancer patients with local recurrence and 76 patients without local recurrence." (PMID 38741069, 2024).
respiratory syncytial virus infection (3 papers, 2016 to 2022). "Study of respiratory syncytial virus infection in SIRT1-deficient BMDC has shown increased fatty acid synthesis leading to mitochondrial dysfunction and reduced antiviral response." (PMID 35849243, 2022). "In respiratory syncytial virus infection, Sirt1 promotes an effective antiviral response through DC cytokine secretion and autophagy-mediated processes, providing an option for a novel vaccination strategy, such as a Sirt1-activating viral vaccine." (PMID 28018344, 2016). "SIRT1−/− bone marrow dendritic cell showed further decreases in MMP, ATP levels and generation of ROS during respiratory syncytial virus infection, leading to inappropriate metabolic processes and enhancement of the pathogenic responses." (PMID 35915458, 2022).
rhabdomyosarcoma (3 papers, 2014 to 2021). A rare aggressive malignant mesenchymal neoplasm arising from skeletal muscle. "Using siRNA to knock down SIRT1 and SIRT2, we show that the expression of both proteins is crucial for the survival of rhabdomyosarcoma cells and that the loss of SIRT1 expression results in a decreased LC3II expression." (PMID 25341037, 2014). "Han found that SIRT1 inhibited viral RNA transcription and translation in enterovirus 71 (EV 71, a RNA virus)-infected human rhabdomyosarcoma (RD) cells." (PMID 32344708, 2020). "In conclusion, our study demonstrates that SIRT1 and SIRT2 expression and activity are crucial for the survival of synovial sarcomas and rhabdomyosarcomas, and that SIRT1 and SIRT2 inhibition impairs the autophagy process inducing cell death." (PMID 25341037, 2014). "SIRT1 and SIRT2 mRNA expressions in the rhabdomyosarcoma cell lines RD, RH30 and RMS were the lowest among the samples examined." (PMID 25341037, 2014). "In the present paper, we have investigated the expression and activity of SIRT1 and SIRT2 in synovial sarcomas and rhabdomyosarcomas, and we evaluated the effects of sirtuin modulation with the small-molecule tenovin-6 and with SIRT1 and SIRT2 siRNA." (PMID 25341037, 2014). "Our results show that SIRT1 and SIRT2 expressions are crucial for the survival of synovial sarcomas and rhabdomyosarcomas, and demonstrate that the pharmacological inhibition of sirtuins impairs the autophagy process and induces tumor cell death." (PMID 25341037, 2014).
Senile plaques (3 papers, 2022 to 2025). Senile plaques are extracellular deposits of amyloid in the gray matter of the brain. "SIRT1 overexpression, furthermore, reduces AD pathology and decreases the formation of β-amyloid protein and senile plaques in APPSWE/ind (J20) and APPswe/PS1M146L (APP/PS1) mice." (PMID 35269588, 2022). "SIRT1 levels are brain region-dependent in AD, being able to degrade the Aβ peptide in primary astrocytes and to reduce ROS and peroxidation levels in APP/PS1 AD model, decreasing senile plaques and improving learning and memory activities." (PMID 36755296, 2023).
spinal cord ischemia (3 papers, 2018 to 2026). Reduced blood flow to the spinal cord which is supplied by the anterior spinal artery and the paired posterior spinal arteries. "Notably, MLN4924, a potent inhibitor of the NEDD8-activating enzyme, significantly attenuates oxidative stress and neuronal cell death by regulating SIRT1 expression during spinal cord ischemia-reperfusion injury." (PMID 34257819, 2021).
synovial sarcoma (3 papers, 2013 to 2021). "SIRT1 was mostly expressed in synovial sarcomas and undifferentiated pleomorphic sarcomas (75% and 67%)." (PMID 34638362, 2021). "We found that SIRT1 is overexpressed in synovial sarcoma tumors and synovial sarcoma cell lines in comparison with normal mesenchymal cells." (PMID 25341037, 2014). "We show that SIRT1 is overexpressed in synovial sarcoma biopsies and cell lines in comparison with normal mesenchymal cells." (PMID 25341037, 2014).
thyroid (3 papers, 2020 to 2025). "Further recruitment of GD patients with orbitopathy will be needed to explore the association between SIRT1 levels and thyroid-associated orbitopathy." (PMID 32485674, 2020). "SIRT7 promotes thyroid tumorigenesis through DBC1/SIRT1 axis phosphorylation and activation of AKT and p70S6K1." (PMID 36523971, 2022).
ulcers (3 papers, 2024 to 2025). "Furthermore, SIRT-1 had decreased levels in the ulcer group, indicating impaired cellular stress responses." (PMID 40563542, 2025). "Similarly, this study demonstrated that the levels of SIRT-1, PGC-1α, and FOXO1 were decreased in response to ethanol-induced ulcers." (PMID 40867886, 2025). "Likewise, this study found that gene expression of Sirt-1, PGC-1α, and HO-1 had been downregulated while FOXO1 expression was upregulated as a response to ethanol-induced ulcers." (PMID 39314751, 2024).
acute promyelocytic leukemia (2 papers, 2013 to 2020). An aggressive form of acute myeloid leukemia (AML), characterized by arrest of leukocyte differentiation at the promyelocyte stage, due to a specific chromosomal translocation t(15;17) in myeloid cells. "SIRT1 expression is decreased in neutrophils differentiated from acute promyelocytic leukemia cells, suggesting that it may be expressed at low levels in this cell type." (PMID 24386389, 2013).
aging (2 papers, 2021 to 2025). A developmental process that is a deterioration and loss of function over time. "Since mitochondrial dysfunction in skin cells is believed to cause an increase in reactive oxygen species levels and may be a cause of skin aging, activation of the SIRT1–mitochondrial axis by fisetin may lead to keratinocyte improvement and activation." (PMID 34207142, 2021). "It is reported that MSC‐derived extracellular vesicles or EXOs improve various diseases via upregulating SIRT1 signalling, such as spinal cord injury, lung injury and aging‐related vascular diseases, whereas the effect of MSC‐EXOs on SIRT1 expression in skeletal muscle remained unclear." (PMID 39871746, 2025).
airway allergy (2 papers, 2019 to 2022). "Further evidence of the pro-inflammatory role of SIRT1 in DCs derives from another study on airway allergy, Legutko and colleagues showed that SIRT1 is responsible for TH2 cells activation by DCs via PPAR-γ repression." (PMID 35457169, 2022).
ataxia telangiectasia (2 papers, 2024 to 2026). Ataxia-telangiectasia is the association of severe combined immunodeficiency (affecting mainly the humoral immune response) with progressive cerebellar ataxia. "For example, overexpression of SIRT6 instead of Rad51 or NBS1 rescues HR repair in ageing cells, and restoration of the NAD+/SIRT1 pathway improves healthspan in Ataxia-telangiectasia models via mitophagy and DNA repair." (PMID 39394181, 2024).
Atopic Dermatitis (2 papers, 2016 to 2021). "AhR and NAD+-dependent deacetylase Sirtuin 1 (SIRT1) were analyzed in different disorders such as human vascular senescence and atopic dermatitis." (PMID 27243009, 2016). "Combined activation of SIRT1 and AhR/AKT improved skin barrier repair and the therapeutic effects of coal tar on atopic dermatitis." (PMID 27243009, 2016).
Bowen's disease (2 papers, 2020).
brain edema (2 papers, 2022 to 2024). Increased intracellular or extracellular fluid in brain tissue. "NLRP3 inflammasome and Sirtuin 1 (SIRT1) activation are affected by RSV, which alleviates brain edema and improves mental function." (PMID 38427213, 2024).
cardiopulmonary disease (2 papers, 2019 to 2022). "SIRT1 functions as a protector from PM exposure, whereas PIR acts as a predictor of PM-induced cardiopulmonary disease." (PMID 31299012, 2019). "It is suggested that the SIRT1‐SREBP‐1‐PIR‐NLRP3 axis may be related to the chronic inflammation of COPD, SIRT1 can be used as a protective agent for PM exposure, and PIR can be used as a predictor of cardiopulmonary diseases induced by PM." (PMID 36444628, 2022).
cerebellar ataxia (2 papers, 2016 to 2022). A neurological syndrome characterized by clumsy and uncoordinated movement of the limbs, trunk, and cranial muscles. "Pharmacological activation of SIRT1 with resveratrol significantly reduces motor incoordination of Machado‐Joseph disease mice, a degenerative disorder characterized by cerebellar ataxia." (PMID 35875858, 2022). "We show that CR alleviation of MJD is mediated by SIRT1, highlighting the benefits of increasing SIRT1 expression or activity to alleviate this and potentially other spinocerebellar ataxias." (PMID 27165717, 2016). "Nevertheless, until now the protective role of SIRT1 in other polyglutamine diseases, namely spinocerebellar ataxias, had not been investigated." (PMID 27165717, 2016).
chorioamnionitis (2 papers, 2023 to 2024). A morphologic finding indicating inflammation of the fetal sac membranes. "Specifically, we predicted that EPO, EPOR, MLTR1, SIRT1, HIF1α and HIF2α alterations after chorioamnionitis (CHORIO) would reflect relative changes observed in human preterm infants." (PMID 37546540, 2023).
Chronic colitis (2 papers, 2023 to 2024). A chronic inflammatory disease of the large intestine (colon, cecum and rectum). "However, the administration of BMS-477118 at either low or high doses to rats with chronic UC resulted in increased levels and activity of SIRT1 compared to the untreated chronic colitis group." (PMID 39359253, 2024).
Cockayne syndrome (2 papers, 2022 to 2023). A multisystem condition characterized by short stature, a characteristic facial appearance, premature aging, photosensitivity, progressive neurological dysfunction, and intellectual deficit. "The strong correlation among PARP1 overactivation, limiting NAD+ pools and inhibition of SIRT1 activity is observed in a broad spectrum of human diseases, including xeroderma pigmentosum group A, progeroid diseases, ataxia telangiectasia and Cockayne syndrome." (PMID 37165408, 2023).
complication (2 papers, 2015 to 2020). Any disease or disorder that occurs during the course of, or because of, another disease, treatment, or procedure. "As loss of SIRT1 production represents an important event in the pathogenesis of chronic diabetic complications 20,27, SIRT1 holds the potential to be used as a drug target for treating such complications." (PMID 25753689, 2015). "We also discuss whether modulation of SIRT1 can serve as a therapeutic strategy to treat diabetic vascular complications." (PMID 33304318, 2020). "Besides, except for SIRT1, there are still other members of the sirtuin family (e.g., SIRT3, SIRT6, and SIRT7) that are active in modulating vascular function, which inspires further works to investigate their associations with oxidative stress and diabetic vascular complications." (PMID 33304318, 2020).
congenital hypothyroidism (2 papers, 2022 to 2025). A thyroid hormone deficiency present from birth. "The present study aimed to investigate the expression, role, and underlying mechanism of action of sirtuin 1 (SIRT1) in congenital hypothyroidism (CH)." (PMID 35383535, 2022).
coronary arterial stenosis (2 papers, 2016 to 2025). "However, the exact relationship between SIRT1 expression and coronary arterial stenosis is poorly understood." (PMID 27123454, 2016).
Crohn disease (2 papers, 2020 to 2022). A gastrointestinal disorder characterized by chronic inflammation involving all layers of the intestinal wall, noncaseating granulomas affecting the intestinal wall and regional lymph nodes, and transmural fibrosis. "In addition, miR-133b expression and SIRT1 activation have been also associated with a number of fibrotic conditions including Crohn’s disease, renal and skin fibrosis." (PMID 32655835, 2020).
dengue (2 papers, 2021 to 2025). "Melatonin has mitochondrial-protective effects like sirtuin 1 (SIRT1) and autophagy modulation along with several in vitro reports of dose-dependent suppression of dengue replication across serotypes." (PMID 41009534, 2025).
Down syndrome (2 papers, 2018 to 2021). "Resveratrol has also shown beneficial effects in several in vitro and in vivo models of neuropathies such as Alzheimer's, Down syndrome, cognition impairments, and aging via modulation of SIRT1-AMPK-PGC1-α pathway." (PMID 34336094, 2021). "In hippocampal progenitor cells from a Down syndrome mouse model and cells derived from patients with Down’s syndrome, EGCG could also sustain and enhance mitochondrial functions by up-regulating PGC-1α/SIRT1/AMPK axis as well as increasing SIRT1-dependent PGC-1α deacetylation." (PMID 29373584, 2018).
dwarfism (2 papers, 2018 to 2024). "Additionally, SIRT1 acts at the brain level as a link between somatotropic signaling and calorie restriction, and brain SIRT1 knockouts displayed dwarfism and reduced plasma GH and IGF-I levels." (PMID 38892461, 2024). "Additionally, SIRT1 acts at the brain level as a link between somatotropic signaling and calorie restriction, and brain-specific Sirt1 knockout mice have dwarfism and reduced plasma GH and IGF-I, displaying similar phenotypes to those of long-lived mutant mice." (PMID 30538673, 2018).
edema (2 papers, 2024 to 2025). An abnormal accumulation of fluid beneath the skin, or in one or more cavities of the body. "It was found that the symptoms of pulmonary edema were significantly alleviated in the H/R rats treated with miR-141-3p mimic, while further overexpression of SIRT1 or Beclin-1 could reverse the effects." (PMID 38261732, 2024).
female infertility (2 papers, 2015 to 2021). Diminished or absent ability of a female to achieve conception. "FOXO3A is a substrate for SIRT1, and deletion of SIRT1 results in female infertility." (PMID 25658474, 2015).
fibromyalgia (2 papers, 2025). A chronic disorder of unknown etiology characterized by pain, stiffness, and tenderness in the muscles of neck, shoulders, back, hips, arms, and legs. "In contrast, increased SIRT1 signalling has been shown to have antinociceptive, anti-inflammatory and antioxidant effects in chronic pain models, including those related to fibromyalgia." (PMID 41470214, 2025). "Fibromyalgia is a biologically complex syndrome involving oxidative stress, low-grade systemic inflammation, alterations in the gut microbiota and dysregulation of the SIRT1-mediated signalling axis." (PMID 41470214, 2025).
gastrointestinal adenoma (2 papers, 2021). "Interestingly, autopsies at the time of “natural death” showed that the incidence of gastrointestinal adenoma was approximately 60% in SIRT1 overexpressing (SIRT1-OE) mice as compared to 30% in wild-type (WT) mice." (PMID 35434708, 2021). "Nevertheless, the prevalence of gastrointestinal adenomas was significantly lower in SIRT6-tg and SIRT1 + 6-tg mice both at 25 months of age and at natural death." (PMID 34050173, 2021). "The gastrointestinal adenoma induced in the SIRT1-OE mice is most likely independent of aging since the percentage of disease was not reflected in the WT mice." (PMID 35434708, 2021).
Giant Cell Arteritis (2 papers, 2021 to 2023). "Recent investigations indicate that SIRT-1 expression is downregulated in individuals with giant cell arteritis, suggesting that SIRT-1 activators could offer a pharmacological opportunity for treatment." (PMID 38006824, 2023). "Nuclear sirtuins, particularly SIRT-1, an enzyme regulating gene expression to suppress inflammatory responses and oxidative stress under physiological conditions, have emerged as potential therapeutic targets for giant cell arteritis." (PMID 38006824, 2023).
glomerulonephritis (2 papers, 2021 to 2022). A renal disorder characterized by damage in the glomeruli. "Therefore, breaking the PPARβ/δ-SIRT1-COX-2 axis may represent an attractive option for the treatment of glomerulonephritis." (PMID 35888719, 2022).
Graves disease (2 papers, 2020 to 2023). Graves' disease is an autoimmune disorder that leads to overactivity of the thyroid gland (hyperthyroidism).It is caused by an abnormal immune system response that causes the thyroid gland to produce too much thyroid hormones. "Although higher TRAb levels are often found in those GD patients that also have orbitopathy, in our 51 patients with Graves’ disease, there is nobody suffering thyroid-associated ophthalmopathy, so we cannot analyze the association between SIRT1 levels and orbitopathy." (PMID 32485674, 2020). "Compared with healthy controls, patients with Graves’ disease exhibited reduced SIRT1 expression and activated NF-κB pathway in their peripheral blood." (PMID 37483618, 2023). "Little has been reported regarding the role of SIRT1 in Graves’ disease, a classic autoimmune thyroid disease." (PMID 37483618, 2023). "FOXP3 and miR-23a-3p were significantly downregulated in patients with Graves’ disease, whereas SIRT1 and RORγt were upregulated." (PMID 37483618, 2023). "Further studies showed that the aberrant acetylation of FOXP3, which is regulated by miR-23a-3p by targeting SIRT1, mediated the defective Treg function in patients with Graves’ disease." (PMID 37483618, 2023). "There is a paucity of data about the role of SIRT1 in Graves’ disease." (PMID 32485674, 2020).
hematoma (2 papers, 2013 to 2025). A hematoma is a collection of blood from a vascular structure into an extravascular space. "A previous study also showed that SIRT1 confers hypoxia-induced radioresistance via the modulation of c-Myc stabilization on hematoma cells." (PMID 24223900, 2013).